MALAT1 (metastasis associated lung adenocarcinoma transcript 1)
Diseases named in the same sentence as MALAT1 in open-access papers (continued):
Sharing a sentence is not in itself a finding about the gene and the disease.
cancer (continued). "Nevertheless, our findings reveal that Nischarin expression status is a significant determinant of Malat1 expression and is an important consideration in experiments investigating cancer treatments which function by altering Malat1 function or expression." (PMID 29912916, 2018). "A previous meta-analysis conducted by Tian and Xu (2015) reported that MALAT1 expression was an independent prognostic marker for OS in patients with cancer using univariate and multivariate analyses, those findings in consist with our results." (PMID 29899709, 2018). "These clinical data are consistent with the experimental ones reported for HCC where SIRT1 activation correlates to malignancy through MALAT1, a lncRNA highly expressed in various cancers including HCC." (PMID 30319549, 2018). "MALAT1 is also a poor overall-survival (OS) biomarker in various other types of cancer, which highlights the high potential of MALAT1 as a biomarker for prognostic in PCa." (PMID 29755696, 2018). "MALAT1 is frequently upregulated in several types of cancers and contributes functionally to the development and malignancy of tumor cells." (PMID 30319549, 2018). "MALAT1 targeting in preclinical cancer models has been mainly achieved by the use of synthetic oligonucleotides." (PMID 29739426, 2018). "As expected, MALAT1 levels were significantly higher in cancer samples than in the matching controls (p = 8.0 × 10−7, Wilcoxon signed-rank test)." (PMID 30318443, 2018). "LncRNAs can regulate cancer cell migration by targeting Rho/ROCK signaling and include metastasis-associated lung adenocarcinoma transcript 1 (MALAT1), actin filament associated protein 1 antisense RNA1 (AFAP1-AS1), and maternally expressed 3 (MEG3)." (PMID 29618386, 2018). "We previously demonstrated a link between characteristics of cancer metastasis and gene regulation by MALAT1." (PMID 29632545, 2017). "The clinical value of MALAT-1 in predicting metastasis and/or survival in cancers has been documented by some meta-analysis studies." (PMID 29254244, 2017). "MALAT1 is upregulated in a wide range of types of cancer, including GC, according to the Cancer Genome Atlas (TCGA) database." (PMID 29162158, 2017). "All proposed candidates tended to be upregulated in tumour tissues, with the exception of MALAT1, which was rather diminished in cancer tissues of both data sets." (PMID 28430799, 2017). "Metastasis-associated lung adenocarcinoma transcript 1 (MALAT1) is a long non-coding RNA (lncRNA), and can induce cancer cell proliferation, while lncRNAs, generally are able to act as microRNA (miRNA) sponges." (PMID 28977880, 2017). "In another case, MALAT1 is believed to regulate process of cancer cell migration, cell cycle progression and alternative splicing, etc.." (PMID 27732939, 2017). "Some previously reported cancer-associated lncRNAs, such as HOTAIR, UCA1, and MALAT1, were found to be differentially expressed in our study, but none was in our top, validated list." (PMID 28415559, 2017). "MALAT1 is broadly expressed in normal human tissues and overexpressed in numerous cancers as well as NSCLC." (PMID 28253859, 2017). "The median expression of MALAT1 tended to be lower in cancer tissues compared to normal controls in both sample sets, but the differences were not significant." (PMID 28430799, 2017). "The results demonstrated that the expression of MALAT1 in GC tissues was up-regulated compared to the paired adjacent non-cancer tissues." (PMID 28396617, 2017). "For example, MALAT1 expression is elevated in various types of human cancer, whereas knockdown of MALAT1 expression arrests the cell cycle at the G1/S phase." (PMID 28977880, 2017). "The expression of lncRNA MALAT1 is upregulated in various kinds of cancers such as liver, uterus, lung, breast, prostate, pancreas and cervix." (PMID 29246025, 2017). "In this study, we found changes in the expression of MALAT1 in adjacent gastric normal and cancer tissues through microarrays." (PMID 28077118, 2017).
cancer (continued). "The metastasis-associated lung adenocarcinoma transcript 1 (MALAT1), also referred to as nuclearenriched abundant transcript 2 (NEAT2), is one of the first discovered cancer-associated lncRNAs." (PMID 28938647, 2017). "Further assays indicated that MALAT1 acted as a competing endogenous RNA to upregulate SOX9 expression by sponging miR-101 in DDP-resistant cancer cells, through Wnt signaling pathway." (PMID 29212230, 2017). "The metastasis-associated lung adenocarcinoma transcript 1 (MALAT1), is a highly conserved nuclear ncRNA and a key regulator of metastasis development in several cancers." (PMID 29290978, 2017). "MALAT1 was already known to be correlated with cell proliferation and metastasis in a variety of cancers." (PMID 28077118, 2017). "We obtained the clinical data and MALAT1 gene expression data from the cancer genome atlas (TCGA) using cBioPortal." (PMID 28253859, 2017). "It has been shown that MALAT1 is upregulated in several cancer types, enhancing cancer metastasis, and high MALAT1 expression is correlated with poor prognosis." (PMID 28270163, 2017). "MALAT1 was reported to be specifically up-regulated in many cancers, such as ovarian cancer, gastric cancer, and breast cancer, in several studies." (PMID 27802187, 2017). "MALAT1 accelerates cancer progression by regulating the expression of some ‘metastatic signature’ genes." (PMID 27802187, 2017). "Some meta-analyses focused on the association of lncRNAs such as MALAT-1, AFAP1-AS1, H19, and PVT1 and metastasis as well as prognosis with cancer; all analyzed only the lncRNAs detected in cancer tissues." (PMID 28146578, 2017). "Single cell RNASeq analyses showed that the MTFs express many transcripts implicated in cancer progression, LINE1 retrotransposons, and very high levels of several long non-coding transcripts involved in metastasis (such as MALAT1)." (PMID 28957348, 2017). "Growing evidence has illustrated that MALAT1 played a negligible role in epithelial‐mesenchymal transition (EMT) of diverse cancer cells." (PMID 28444861, 2017). "Metastasis associated lung adenocarcinoma transcript 1(MALAT1) is a long non‐coding RNA, broadly expressed in mammalian tissues including kidney and up‐regulated in a variety of cancer cells." (PMID 28444861, 2017). "For example, knockdown of HOTAIR or MALAT1 with siRNAs inhibits cancer-cell proliferation and increases apoptosis." (PMID 27802187, 2017). "Interference with MALAT1 expression in cancer inhibits tumor growth and metastasis and increases tumor cell apoptosis and sensitivity to radiotherapy." (PMID 27802187, 2017). "Since cancer patients expressing high levels of this lncRNA have a poorer clinical outcome, MALAT1 can be considered a potential prognostic biomarker for various cancers, including BC." (PMID 29165379, 2017). "In particular, known disease lncRNAs, MEG3 and MALAT1, frequently occurred in 9 and 10 cancer types in the top 10% of candidate disease lncRNA lists, respectively." (PMID 29383105, 2017). "MALAT1 is a prognostic marker in several cancers: including lung, breast, pancreas, liver, colon, uterus, cervix, and prostate." (PMID 28671581, 2017). "Many lncRNAs have been associated with controlling gene expression with arguably the best studied lncRNA being MALAT1 and its role in cancer." (PMID 28732076, 2017). "All these data indicated that elevated MALAT-1 achieves a powerful efficacy to aid in the diagnosis of cancers." (PMID 29254244, 2017). "LncRNA MALAT1 is located on Ch11q13 and has been reported to be deregulated and an independent prognostic parameter for survival in various cancers." (PMID 28187000, 2017). "Originally identified as a gene upregulated in metastatic non-small-cell lung cancer cells, human MALAT1 has recently been found overexpressed in many cancers." (PMID 28326190, 2017). "Following radiation treatment, expression of MALAT1 was decreased in radiosensitive but increased in both radioresistant cancer cells and clinical cases." (PMID 28872613, 2017).
cancer (continued). "Further research is needed to determine if NEAT1 plays a direct role in oncogenesis, or if instead the MALAT1/NEAT1 locus is under mutual regulation, with NEAT1 upregulation in cancer being a byproduct of its genomic proximity to MALAT1." (PMID 29113413, 2017). "Expression of the lincRNA MALAT1 is shown for comparison, and although upregulation is seen in some cancers, there is little difference in the “bronchus and lung” group." (PMID 28732076, 2017). "Mounting evidence indicates that MALAT1 is one of the most abundant and well-conserved lncRNAs and is overexpressed in many human malignancies, including cancers of the nasopharynx, breast, prostate, bladder, and endometrium." (PMID 29116025, 2017). "MALAT1 (also known as NEAT2) is involved in the regulation of cell cycle, cell migration, and cancer metastasis." (PMID 28839203, 2017). "Although several other lncRNAs have been reported to promote cancer metastasis, such as the well-characterized MALAT1 and HOTAIR, less evidence exists of lncRNAs acting as inhibitors of this process." (PMID 29078818, 2017). "Progressing findings have suggested that MALAT1 activates the development and progression of cancer by participating in multiple processes including cell proliferation, migration, invasion and apoptosis." (PMID 29190941, 2017). "Our study showed that MALAT1, a lncRNA overexpressed in a wide range of cancers, was upregulated in chemoresistant GC cells." (PMID 29162158, 2017). "Metastasis-associated lung adenocarcinoma transcript 1 (MALAT-1) is one kind of long non-coding RNAs (lncRNAs) that has been recognized as a hallmark of the onset and development of several carcinomas." (PMID 29254244, 2017). "We chose five lncRNAs (HOTAIR, HOXA-AS-2, lincRNA—ROR, MALAT1, and ANRIL) and three mRNA Homeobox A13 (HOXA13), SRY-box 2 (SOX2) and POU class 5 homeobox 1 (POU5F1/OCT4) implicated in a range of cancers, including UBC." (PMID 26800519, 2016). "Long non-coding RNAs (lncRNAs) have also been increasingly implicated in tumor biology, yet beyond studies of previously cancer-associated transcripts such as HOTAIR, MALAT-1, and NEAT-1, their significance in HNSCC is sparsely characterized." (PMID 27323410, 2016). "It is well known that Malat1 is highly expressed in several cancers and overexpression of MALAT1 facilitates cancer cell proliferation and tumour metastasis." (PMID 27374227, 2016). "MALAT-1, a long non-coding RNA, is involved in cell proliferation in cancer cells, so we next measured the cell proliferation after the transfections of plasmids expressing the corresponding asRNA or oligomer RNA into Hela cell and MDA-MB-231 cell." (PMID 27231846, 2016). "On similar lines, several earlier studies have reported that in various cancers MALAT1 influences tumor progression and metastasis by controlling distinct cellular pathways." (PMID 27250026, 2016). "MALAT1, regarded as one of the most familiar oncogenic lncRNAs, was overexpressed in various cancers." (PMID 27777857, 2016). "In accordance with other cancer types, MALAT1 is also up-regulated in ccRCC samples and in RCC cell lines compared to non-tumourous renal tissue or cells." (PMID 27092491, 2016). "Accordingly, differentially expressed lncRNA MALAT1 and pathway analysis of our data also demonstrate the common pathways indicating similar pathophysiological basis between cancer and CVDs." (PMID 27144026, 2016). "For example, MALAT-1 has been primarily studied for its role in cancer cells migration, invasion and metastasis." (PMID 26943769, 2016). "For example, metastasis-associated lung adenocarcinoma transcript 1 (MALAT1), a well-known lncRNA, is markedly overexpressed in CRC and has been suggested as a diagnostic cancer indicator." (PMID 27543107, 2016). "High expression of MALAT-1 is a strong predictor of poor prognosis in early cancers; however, some patients with low MALAT-1 levels also die during the 5-year follow-up period." (PMID 26637808, 2016).
cancer (continued). "Although MALAT1 expression is considered to relating to clinical prognosis of multiple cancers, the specific impact of MALAT1 expression on the outcome of cancer patients still needs to be further investigated." (PMID 27777857, 2016). "For example, MALAT1, a lncRNA with an important role in cell proliferation, migration and invasion, has been found significantly up-regulated in several cancers, including lung, breast, prostate, liver, and colon." (PMID 27148353, 2016). "We found that the expression of small proline-rich protein 2A (SPRR2A) were negatively regulated by MALAT-1 expression and had an influence on cancer metastasis in vivo." (PMID 27586393, 2016). "MiR-206, a tumor suppressor gene in various types cancer, was chosen for further studies given its high upregulation (fold change = 2.78) in response to Malat1 knockdown in NOZ cells compared to the scrambled control." (PMID 27191262, 2016). "Altogether, these results confirm that under in vivo conditions, over expression of MALAT1 enhances the tumorigenic and metastatic properties of cancer cells." (PMID 27250026, 2016). "A total of 12 studies including 1549 patients were recruited to assess the effect of MALAT1 overexpression on OS in different types of cancer." (PMID 27777857, 2016). "Overall, these data point to MALAT1 as a potential independent marker of cancer metastasis and prognosis and as a potential molecular target to control cancer metastasis." (PMID 27148353, 2016). "Data has indicated that MALAT-1 was involved in cancer development through regulation of alternative splicing of its target genes or gene expression." (PMID 27227769, 2016). "MALAT-1 is also reported to have some relationship with cell apoptosis in cancer cells, so, here we detected the effects of asRNA on cell apoptosis in Hela cell and MDA-MB-231 cell." (PMID 27231846, 2016). "Among 848 EZH2-bound lncRNAs in MKN45, the metastatic cell line among the three cell lines examined, we found HOTAIR and MALAT1, which are well documented for their involvement in cancer metastasis." (PMID 26871474, 2016). "Recent studies indicated that the up-regulated MALAT1 is essential for the proliferation and migration in diverse cancer cells." (PMID 27019196, 2016). "We also sought relationships between MALAT1 and genes and proteins expression known to be involved in different steps of MALAT1 pathway dysregulation observed in others types of human cancers." (PMID 27172249, 2016). "MALAT-1 is involved in mRNA splicing and nuclear paraspeckle function in cancer, and contributes to gene expression by regulating mRNA splicing, editing, and export." (PMID 26637808, 2016). "Recent studies found that overexpression of MALAT1 correlated with poor prognosis of patients with nearly all types of cancer." (PMID 27777857, 2016). "As several studies recently suggested that MALAT1 promotes proliferation and metastasis of various cancers by activating the RTK/MAPK/PI3K pathways, we tested possible correlation between Δsv-MALAT1 and various proteins involved in these signalling pathways." (PMID 27172249, 2016). "The expression of MALAT1 is up-regulated in cancers of the lung, breast, pancreas, liver, colon, uterus, cervix and prostate." (PMID 26735578, 2016). "Increased expression of MALAT1 is observed in lung, breast, colon, cervical, colorectal, ovarian, gastric, and other cancer types." (PMID 27144026, 2016). "Metastasis-associated lung adenocarcinoma transcript 1 (MALAT1) and HOX transcript antisense RNA (HOTAIR) are the most studied lncRNAs, which are deregulated in majority of cancers." (PMID 27242964, 2016). "A quantitative meta-analysis was performed using a systematic search of PubMed, Medline and Web of Science databases to identify eligible papers on prognostic value of MALAT1 in cancers." (PMID 27777857, 2016).
cancer (continued). "Some well-known cancer-associated lncRNAs, such as H19, XIST, HOTAIR, MALAT1, MEG3, HNF1A-AS1 and PVT1, have indicated oncogenic and/or tumor suppressive roles like protein-coding genes in various cancers." (PMID 27074572, 2016). "The proposed common pathophysiological basis between cancer and CVDs is strengthened by the role of lncRNAs such as MALAT1, p21, ANRIL, and HOTAIR in the development of cancer as well as in CVDs." (PMID 27144026, 2016). "Recently, a meta-analysis including 1216 participants reported a correlation between high MALAT1 expression and three markers of cancer progression: lymph node metastasis, distant metastasis and survival rate." (PMID 27148353, 2016). "MALAT1, a highly conserved long noncoding RNA and also known as nuclear-enriched transcript 2 (NEAT2), is deregulated in several types of cancers." (PMID 27782152, 2016). "In multiple human cancers, MALAT1 plays a role in carcinogenesis, including tumor cell proliferation, apoptosis, migration and metastasis." (PMID 27191888, 2016). "We performed an overall analysis of the data from studies containing abnormal expression of MALAT-1 and ORs from a variety of cancers." (PMID 26989678, 2016). "The metastasis-associated lung adenocarcinoma transcript 1 (MALAT1) is frequently over-expressed and serves as a prognostic marker in human cancers." (PMID 27486823, 2016). "In this report we show Malat1, an lncRNA previously established to play a critical role in metastasis of cancer cells, to be upregulated in JEV-infected Neuro2a cells." (PMID 26634309, 2015). "The results of our meta-analysis indicate that elevated MALAT1 expression affects the prognosis of cancer patients, and these findings should promote the development of adequately designed prospective studies." (PMID 26420912, 2015). "Elevated MALAT1 expression was associated with poorer DFS, although the role of MALAT1 in cancer development requires further evaluation." (PMID 26420912, 2015). "Elevated MALAT1 expression is correlated with poor OS in various types of cancer, suggesting that this gene is a prognostic factor for different types of cancer." (PMID 26420912, 2015). "Although over-expression of MALAT1 has been reported in multiple cancer types, little is known about the factors which contribute to its up-regulation." (PMID 25613496, 2015). "MALAT1 expression was significantly upregulated in cancer tissues (mean ratio of 2.14-fold, P < 0.01) compared with normal counterparts in KIRC." (PMID 26461224, 2015). "An additional classic oncogenic lncRNA is MALAT1, which regulated the alternative splicing of a subset of pre-mRNAs to promote cancer metastasis." (PMID 25624916, 2015). "The prognostic role of MALAT1 in cancer was evaluated by a meta-analysis of 9 studies including 932 participants." (PMID 26420912, 2015). "Despite the fact that MALAT1 is often overexpressed in human cancers including PCa, its functional role in cancer progression is poorly understood." (PMID 26516927, 2015). "A growing amount of literature has linked deregulation of lncRNAs with diverse human cancers, such as the well-characterized HOTAIR, MEG3, GAS5, H19, and MALAT1." (PMID 25613496, 2015). "Systematic literature searches of PubMed and EMBASE databases were conducted for eligible studies of the prognostic role of MALAT1 in cancer." (PMID 26420912, 2015). "In HCC, however, to date, only a few studies implicated lncRNAs, such as MALAT1, HOTAIR, HOTTIP/HOXA13, H19, HULC, MEG3, in the cancer pathogenesis." (PMID 25686840, 2015). "The conservative of Malat1 sequence indicates it is a house keeping like gene, more and more evidence shows it up regulates in many cancers, and this research also shows Malat1 is highly expression in undifferentiated hematopoietic stem cells." (PMID 26335021, 2015). "In this study, we provided both experimental and clinical evidence to support MALAT1 as a cancer metastasis related molecule and a potential therapeutic target in OSCC." (PMID 26522444, 2015).